APC (APC regulator of Wnt signaling pathway)
Diseases named in the same sentence as APC in open-access papers (continued):
Sharing a sentence is not in itself a finding about the gene and the disease.
colorectal cancer (continued). "Despite the characterisation of many aetiologic genetic changes – such as mutation of APC and genes encoding DNA mismatch repair proteins – the specific causative factors in the development of sporadic colorectal cancer remain unclear." (PMID 19436735, 2009). "Moreover, somatic APC mutations play a rate-limiting and initiating role in the majority of sporadic colorectal cancers." (PMID 19578404, 2009). "Recently, the "two-hit-hypothesis" was challenged in a study of inactivating APC gene mutations in colorectal cancer, in which three hits - including mutations, deletions, and copy number gain - were demonstrated in a subset of the tumors." (PMID 19832985, 2009). "In colorectal cancer cells with inactivating APC hemizygous mutation or activating CTNNB1 heterozygous mutation, the total β-catenin signaling activity seemed dependent also on silencing of SFRP genes by promoter hypermethylation with consistent constitutive WNT signaling." (PMID 18541010, 2008). "Probands with APC mutations outside codon 1250–1464, although exhibiting a less-severe phenotype, are at high risk of having a colorectal cancer at diagnosis indicating that age at diagnosis is as important as the severity of the disease for colorectal cancer morbidity." (PMID 18433509, 2008). "To see whether the L>F and L>K mutations affected the subcellular distributions of BCL9 or BCL9-2, we expressed these proteins in SW480 colorectal cancer cells whose Wnt pathway activity is high, due to mutation of APC." (PMID 18627596, 2008). "Genetic alterations in the APC genes causes predisposition for colorectal cancer (Groden, Cell 1991), and the tumor suppressor function of APC/oncogenic effect of Wnt pathway is clearly demonstrated in APCmin transgenic mice where numerous adenomas form in the intestine." (PMID 18478098, 2008). "Somatic mutations in APC underlie the majority of cases of sporadic colorectal cancers." (PMID 17595655, 2007). "Colorectal cancer, smoking history and APC truncation mutation status." (PMID 16545110, 2006). "Activation of the Wnt pathway plays a central role in the aetiology of most colorectal cancers and is often the result of mutations in the N-terminal domain of the APC gene, that lead to partial or complete loss of this region and thereby to loss of the β-catenin regulating function." (PMID 16356174, 2005). "Notably, PSG9 was expressed in the morphologically normal mucosa of FAP patients with APC germline mutations, while its expression was rarely detectable in normal mucosa of sporadic colorectal cancers using in situ hybridization." (PMID 15982419, 2005). "However, it becomes clear that some polymorphisms like the APC gene in colorectal cancer in the Ashkenazim and the paraoxonase gene in coronary heart disease in type 2 diabetes are not entirely harmless." (PMID 12085189, 2002). "The association of AEMs with colorectal cancer is intriguing, and we speculate that it may be a manifestation of mutational mosaicism of the APC gene, perhaps associated with a constitutional defect in DNA mismatch pair." (PMID 8956794, 1996). "However, how gastric tumors achieve WNT niche independence remains unclear, as mutations on APC or CTNNB1—common mechanisms of ligand-independent WNT activation in colorectal cancer—are infrequent in gastric cancer." (PMID 41398956, 2025). "Additionally, research indicates that tumor development and metastasis in colorectal cancer are influenced by the activation of the Wnt pathway, primarily through mutations in key regulatory genes such as adenomatous polyposis coli (APC), which is followed by an increase in VEGF expression." (PMID 40784879, 2025). "Thus, AXIN2 restricts Wnt signaling to some extent even in APC mutated colorectal cancer cells." (PMID 39022865, 2025). "In addition, they found that hyperactivation of the WNT/β-catenin pathway could lead to selective death of colorectal cancer cells with APC mutations." (PMID 40240755, 2025).
colorectal cancer (continued). "Thus, this case may also benefit from multikinase KRAS (on) inhibitors, which could have significant implications for the management of colorectal cancer where pathogenic APC mutations are enriched." (PMID 38791940, 2024). "Critically, nonsense mutations in the APC gene upstream of the Axin binding site are considered initiating events in colorectal carcinoma, and it is estimated that over 80% of all CRC cases harbor such a mutation." (PMID 39095874, 2024). "One of our interesting findings is that de novo APC c.4666dupA (p.Thr1556AsnfsX3), which has been reported to cause an aggressive Gardner syndrome in a 2-year-old European boy, reproduced as a pancreatic, duodenal and colorectal cancer phenotype in a 104-year-old Japanese woman." (PMID 36896836, 2023). "This principle has previously been demonstrated to underscore regional patterns of colorectal cancer emergence in patients with FAP where second-hit mutations to APC leading to further dysregulation of Wnt signaling are selected to preserve some residual APC function." (PMID 37943618, 2023). "For all three datasets surveyed (PDX compendium, patient tumor metastasis compendium, TCGA), one gene, APC, was consistently enriched for mutation events (p < 0.01, one-sided Fisher’s exact test) in the s1 subtype, due in part to the relative enrichment of s1 for colorectal cancers." (PMID 36731467, 2023). "These together suggest that although IFNγ can target colorectal cancer stemness, it may hold true for only a small proportion of sporadic colorectal cancer patients, and additional strategies are needed to enhance the sensitivity of colorectal cancer cells carrying APC mutation to IFNγ treatment." (PMID 37671945, 2023). "The primary mechanism leading to hyper-activation of Wnt signaling in cancer is loss of function (LoF) in APC, an event that is commonly observed in hereditary (familial adenomatous polyposis) and sporadic colorectal carcinomas (CRC)." (PMID 37255594, 2023). "Similarly, Wnt and RA signaling pathways have been associated with the development of human colorectal carcinoma with adenomatous polyposis coli (APC) mutations, as the upregulation of Wnt signaling by downregulated RA signaling resulted in immature APC-mutant colon tissue." (PMID 36678247, 2023). "Similarly, quercitrin does not potentiate the pathway in SW480 cell lines, a colorectal cancer cell line harboring an APC mutation that leads to Wnt signaling overactivation, suggesting that quercitrin might not contribute to tumor formation." (PMID 36292931, 2022). "Colorectal carcinoma cells (CRC) are known for their increased nuclear β-catenin when APC, a destruction complex protein, is mutated." (PMID 35632546, 2022). "Indeed, in humans the most common driver mutation for colorectal carcinoma is related to a mutation in the tumor suppressor gene APC, leading to the inactivation of APC and activation of the Wnt signaling pathway, with a consequent stabilization of β-catenin and its translocation to the nucleus." (PMID 35889921, 2022). "However, the analysis of all APC mutations in a large colorectal cancer cohort indicates that most mutations are C > T substitutions at CpG sites, pointing to a major role for the endogenous clock-like deamination of methylated cytosines (SBS1) in the induction of cancer driving mutations." (PMID 34745228, 2021). "In addition, mutation of APC is related to the stage of colorectal cancer." (PMID 34306002, 2021). "The findings in the present study provide lipid biomarkers of cancerous and normal cells and enhanced insight into the metabolic effects of inactivating APC mutations commonly found in colorectal cancer tumours, and thus could inform therapeutic strategies in the future." (PMID 33620068, 2021).
colorectal cancer (continued). "Moreover, the most common gene mutated in colorectal cancer is the adenomatous polyposis coli (APC) tumor suppressor gene and the mechanisms of APC inactivation include hypermethylation of CpG sites in APC promotor and decreased translation due to inhibition by microRNA." (PMID 29997595, 2018). "In addition to APC mutations, colorectal cancers also exhibit aberrant APC expression due to loss of heterozygosity (LOH); LOH may also be acquired in colorectal adenomas as a consequence of somatic mutation." (PMID 29652830, 2018). "The most prevalent genetic changes in colorectal cancers are biallelic APC mutations; less frequently, the WNT pathway may be activated in colorectal cancers by another genetic mechanism consisting of the gain-of-function mutations of the gene encoding β-catenin (CTNNB1)." (PMID 29652830, 2018). "However, additional susceptibility variants were detected in the APC gene, suggesting that other variants may contribute to the increased prevalence of colorectal cancer in the AJP." (PMID 28502252, 2017). "Loss-of-function mutation in adenomatous polyposis coli (APC) tumor suppressor or gain-of-function mutation in β-catenin oncogene have long been recognized to lead to constitutively active Wingless/Int-1 (Wnt) signaling, giving rise to a high risk of colorectal cancer development." (PMID 28245560, 2017). "Moreover, ASE of APC may contribute to common forms of colorectal cancer, as colorectal cancer risk has been shown to increase along with increasing ASE imbalance." (PMID 27683109, 2016). "Hence, intestinal microbiota/LPS stimulation was a risk factor for development of colorectal cancer in APC mutation population, which might provide a new strategy for the prevention of colorectal cancer." (PMID 26760960, 2016). "Mutations in APC may result in colorectal cancer, prostate cancer, and other cancers." (PMID 27930734, 2016). "In particular, colorectal cancer, desmoid tumor, gastric cancer, melanoma, hepatocellular, prostate, thyroid, ovarian, endometrial cancer, and some subsets of breast cancers harbour β-catenin-stabilizing mutations, including germline APC gene and somatic CTNNB1 gene mutations." (PMID 26056602, 2015). "Most cases of colorectal cancer appear to be caused by somatic mutations, but a small number of cases are the result of germ-line mutations in the tumor-suppressor gene adenomatous polyposis coli (APC) which causes an inherited condition called familial adenomatous polyposis (FAP)." (PMID 25836260, 2015). "However, the association between genetic variants (A/T) in the APC gene D1822V polymorphism and colorectal cancer (CRC) susceptibility remains unknown." (PMID 24959234, 2014). "Thus APC mutations generally play a role in the initiation of colorectal cancers." (PMID 24943349, 2014). "The importance of these Wnt gatekeepers has been demonstrated in colorectal cancer, the cancer most commonly associated with aberrant Wnt signaling where re-expression of Wnt antagonists appeared to override strong downstream mutations in APC (adenomatous polyposis coli), and induce apoptosis." (PMID 22363760, 2012). "Notably, a particular severe phenotype, involving a higher number of polyps and an earlier onset of colorectal cancer, has been observed in patients carrying mutations in the most mutated codon (codon 1309) of the APC gene, with a population frequency ranging from 0% to 29%." (PMID 20649969, 2010).
colorectal cancer (continued). "In colorectal cancer, at least, the high frequency of APC and other mutations that stabilise β-catenin might, therefore, be expected to lead to induction of these Wnt antagonists, including the sFRPs, if they were not suppressed by other mechanisms before the onset of tumorigenesis." (PMID 16523202, 2006). "Increased β-catenin signalling (as a result of APC mutation) is a common causative event in colorectal cancer, and it is conceivable that DC switching could contribute to β-catenin dysregulation and so play a contributory role in the initiation of the early stages of colorectal tumorigenesis." (PMID 17088906, 2006). "Colorectal cancer (CRC) remains largely refractory to immune-checkpoint blockade, with adenomatous polyposis coli (APC) mutations present in 80%–90% of cases." (PMID 41486293, 2026). "Colorectal cancer (CRC) arises through interactions between driver mutations, such as in APC and KRAS, and the tumor microenvironment (TME), including inflammatory factors." (PMID 41285904, 2025). "To explore single-cell transcriptional alterations in CRC, we generated scRNA-seq profiles from 10 normal samples and 23 colorectal cancer samples (6 cases APC wild-type) using 10× genome sequencing data." (PMID 40357363, 2025). "Because APC tumor suppressor defects in approximately 80% of colorectal cancers (CRCs) activate the Wnt/β-catenin pathway, we studied SOX9 inactivation in CRC biology." (PMID 40179020, 2025). "Adenomatous polyposis coli (APC) inactivation has been observed in numerous cancer types and is considered a pivotal initiating event in colorectal cancer." (PMID 40136551, 2025). "The APC, a TSG, is usually changed in colorectal cancers, and this mutation stimulates the Wingless/Wnt pathway." (PMID 40755497, 2025). "The APC gene, located on chromosome 5q, is one of the key genes involved in the development of colorectal cancer (CRC)." (PMID 40740242, 2025). "Recurrent APC mutations, specifically p.R302* and p.R232*, and AMER1 (p.R631*) mutations were primarily observed in colorectal cancer." (PMID 39748775, 2025). "For example, inactivation of APC leads to β-catenin accumulation and overactivation of Wnt target genes, promoting colorectal cancer development." (PMID 40796737, 2025). "Activation of the WNT signaling pathway is essential for the initiation of colorectal cancer, and the APC (APC regulator of WNT signaling pathway) gene on chromosome 5q22.2 acts as a gatekeeper for this pathway." (PMID 40004106, 2025). "Functional studies have demonstrated a damaging effect via binding disruptions of the TF YY1 and impaired activity of the APC promoter in gastric and colorectal cancer cell lines." (PMID 40470206, 2025). "Biallelic inactivation of the APC gene, loss of heterozygosity (LOH), is required for the development of colorectal cancer, and germline mutations in APC cause familial adenomatous polyposis." (PMID 40004106, 2025). "Mutations in the APC gene have been cataloged in nearly 50% of colorectal cancers, while mutations in WNT ligand genes are present in nearly 14% of colorectal cancers." (PMID 40165370, 2025).
colorectal cancer (continued). "For instance, in colorectal cancer, BRAFV600E mutations often co-occur with RNF43 mutations and infrequently with APC mutations." (PMID 40735046, 2025). "Initially, known hereditary cancer syndromes and their associated pathogenic variants were thought to be related to a single tumor type, such as BRCA1/2 in BC and APC or the DNA mismatch repair genes in colorectal cancer." (PMID 40564925, 2025). "For colorectal cancer, we were able to analyze the effect of mutation-CNV co-occurrence on patient prognosis for three genes, namely APC, FBXW7, and PIK3CA." (PMID 41415395, 2025). "The APC, a TSG, is usually changed in colorectal cancers, and this mutation activates the Wingless/Wnt pathway." (PMID 40761498, 2025). "It is worth noting that c-Myc is a well-established transcriptional target of the APC-Wnt signaling pathway, which represents a key oncogenic driver in colorectal cancer progression." (PMID 41188443, 2025). "In colorectal cancer (CRC), Wnt signaling is a key driver of tumor progression, with its dysregulation commonly occurring due to Adenomatous Polyposis Coli (APC) mutations that stabilize β-catenin, leading to the constitutive activation of Wnt target genes." (PMID 40917745, 2025). "For example, although most colorectal cancers exhibit adenomatous polyposis coli (APC) mutations affecting the WNT signaling pathway, β-catenin, a downstream biomolecule of APC, has emerged as an effective therapeutic target." (PMID 39880378, 2025). "This is yet another mechanism by which germline APC mutations, such as those seen in FAP, disrupt the ability to mount successful immune surveillance preventing the progression of polyps to colorectal cancer." (PMID 39944699, 2025). "In cancer, they promote colorectal cancer progression through the APC/β-catenin pathway, are overexpressed in non-small-cell lung cancer, are associated with poor prognosis in Ewing’s sarcoma, and have been reported to facilitate bone cancer pain." (PMID 40493617, 2025). "Overall, methylation of key tumor suppressor genes in colorectal cancer was most clearly observed in exon 1A of APC, exon 1 surroundings, and upstream regions of MLH1." (PMID 40004106, 2025). "Hence, we hypothesized that in addition to aneuploidy-based loss of Smad2, Smad4, and Dcc in these five colorectal carcinoma tumors, as all our colorectal carcinoma tumors had two copy loss of the floxed Apc allele, the somatic APC copy loss event may also have affected the three known TSGs." (PMID 41051921, 2025). "Typical of MMR-proficient colorectal adenocarcinomas (and adenomas) in general, APC was mutant in all tumors but one (colorectal carcinoma of individual III.6 from HNPCC20), and KRAS, too, was frequently affected." (PMID 41023686, 2025).